LAG3 (lymphocyte activating 3)
Diseases named in the same sentence as LAG3 in open-access papers (continued):
Sharing a sentence is not in itself a finding about the gene and the disease.
lymphoma (continued). "In contrast, while LAG-3+ T cells exhibited the similar phenotype in FL biopsy specimens to tonsil tissue, the number of CD8+LAG-3+ cells was increased in lymphoma biopsies." (PMID 28977875, 2017). "We found that the majority of LAG-3+ T cells were TEM (CD45RA-CCR7-) cells in both tonsil and lymphoma tissues." (PMID 28977875, 2017). "Compared to lymphoma tissues, tonsils had a significant higher number of TN (CD45RA+CCR7+) or TCM (CD45RA-CCR7+) cells that expressed LAG-3." (PMID 28977875, 2017). "Although it is assumed that the TIME of cHL and DLBCL is not identical, LAG‐3 can be suggested to be a uniquely activated immune checkpoint in the immune depleted microenvironment of lymphomas." (PMID 37326144, 2023). "Besides, lymphocyte activation gene-3 (LAG-3) knockout CD19-specific CAR-T cells by CRISPR-Cas9 elicited strong antigen-specific anti-tumor effects in vitro and lymphoma Raji cell-bearing NOD-Prkdcscid Il2rgnull (NPG) mice." (PMID 34321099, 2021). "In addition to AML, intertumoral and peripheral blood lymphocytes from HL patients also expressed high levels of LAG-3, and deletion of CD4+LAG-3+ T cells improved lymphoma-specific CD8+ T cell responses." (PMID 31186046, 2019). "However, we observed that intratumoral LAG-3+ T cells expressed TEMRA markers (CD45RA+CCR7-), suggesting a terminal differentiation status of LAG-3+ T cells in lymphoma." (PMID 28977875, 2017). "To further confirm the effects of dual anti-LAG3 and anti-PD1 blockade in delaying tumor growth using an additional tumor model, we further tested antibody blockade in the context of the subcutaneous OVA-expressing lymphoma EG7 tumor." (PMID 26318293, 2015). "Similarly, the expression of LAG-3 and TIM-3 has been reported in multiple lymphoma subtypes." (PMID 36959853, 2023). "Moreover, we performed multicolor flow cytometry to examine the role of miR130b in immune checkpoint genes including PD-L1, CD80, 4-1BBL, LAG3, TIGHT, TIM3, and VISTA on lymphoma cells in the miR130b-overexpressing DB co-culture system and miR130b-knockdown OCI-ly10 co-culture system." (PMID 35301282, 2022). "However, the anti-tumor effects of the LAG-3 knockout CD19 CAR-T cells were similar to standard CAR-T cells, probably indicating that LAG-3 is not the primary checkpoint by which lymphoma cells induce T cell exhaustion." (PMID 32325898, 2020). "The anti-LAG-3 antibody BMS-986016 is currently being used in phase I and phase II clinical trials in combination with nivolumab in subjects with relapsed or refractory HL, and relapsed or refractory diffuse large B cell lymphoma (DLBCL) (NCT02061761) or as a single drug in lymphoma (NCT03489369)." (PMID 31867006, 2019). "LAG-3 expression could be substantially upregulated on CD4+ or CD8+ T cells by IL-12, a cytokine that has been shown to induce T-cell exhaustion and be increased in the serum of lymphoma patients." (PMID 28977875, 2017). "The frequencies of PD-1+LAG-3+ heavily exhausted T cells among CD4+ and CD8+ T cells was higher in the blood of cattle with B-cell lymphoma over that of BLV-uninfected and BLV-infected cattle without lymphoma." (PMID 29914540, 2018). "However, expression of the exhaustion markers PD-1, LAG-3, and TIM-3 were not upregulated on CXCR5 CAR-T compared to SP6 CAR-T cells when we analyzed the persistence of CXCR5 CAR T cells in vivo at the time of lymphoma cell outgrowth." (PMID 33431832, 2021). "Further experimentation is required to confirm immunomodulatory role of PD-1 and LAG-3 on bovine T cells, but it seems that these immunoinhibitory receptors might play the major role in CD4+ and CD8+ αβ T-cell subsets, not in γδ T cells, in cattle bearing lymphoma." (PMID 29914540, 2018).
viral infection (46 papers, 2013 to 2024). "For LAG-3, which is directly associated with a reduced immune response to viral infections, we observed a trend toward higher expression in patients treated with anti-TNF, in contrast to patients treated with vedolizumab." (PMID 38155275, 2023). "Since LAG-3 plays a crucial part in immunological control, it has been shown that abnormal LAG-3 expression is associated with a number of illnesses, including cancer, persistent viral infection, parasitic infection, and autoimmune." (PMID 36677919, 2023). "Under conditions of prolonged chronic viral infections and sustained antigen exposure, LAG3 remains highly expressed on both CD4+ and CD8+ T cells, contributing to T cell exhaustion." (PMID 38592036, 2024). "Exhausted T cells in chronic viral infection or a tumor microenvironment express high levels of PD-1 and Lag-3, which suppress activation to keep T cells hypo-responsive." (PMID 39234253, 2024). "If there is persistent viral infection or stimulation from tumor antigens, LAG-3 is expressed simultaneously with other immune checkpoints on the surfaces of both CD4+ and CD8+ T cells, indicating possible T cell dysfunction." (PMID 37841254, 2023). "Further, TRM cells exhibit elevated LAG3 expression during viral infections; and blocking the LAG3 pathway can restore the antiviral response and improve TRM cell functions." (PMID 36993960, 2023). "Intracellular production of IL-2, IFN-g, and TNF, and often severely reduced in persistent viral infections, and T cells also express large numbers of inhibitory receptors, including PD-1 (programmed cell death-1) and Lymphocyte-Activation Gene 3 (Lag-3)." (PMID 36678799, 2023). "In this case, research has mainly focused on treating LAG-3-blocking antibodies during chronic viral infections." (PMID 36680187, 2023). "Nonetheless, when directly comparing LAG-3−/− T cells to WT T cells in adoptive transfer experiments, LAG-3−/− T cells display enhanced effector function compared to WT T cells during viral infections." (PMID 35265944, 2022). "In contrast, the exhausted genes were up‐regulated after viral infection (e.g. Havcr2, Lag3, Cd96 and Ctla4)." (PMID 35051311, 2022). "Further unbiased investigation into the most expressed genes per cluster revealed a plethora of genes previously reported in the context of viral infections, such as Il7r, Tcf7, Zeb2, Klrg1, Gzma, Gzmb, Gzmk, Vim, Lgals3, Tox, Lag3, Pdc1, Id3." (PMID 35185882, 2022). "Other immune checkpoints, such as cytotoxic T-lymphocyte associated protein 4 (CTLA4), lymphocyte activating 3 (LAG3) and indoleamine 2,3-dioxygenase 1 (IDO1) have been also studied in immunosuppressive viral diseases such as PMWS and CSF." (PMID 34046040, 2021). "Chronic viral infection is associated with T cell exhaustion manifested by sustained expression of inhibitory receptors such as PD-1, 2B4 (CD244), CTLA4, LAG3, TIM3, CD16022." (PMID 32020034, 2020). "In the bacterial exposure (SR) and viral infection (Flu) models, we observed an increased proportion of IL-10+ LAG3+CD49b+ T cells that are CD8+, which is the predominant population in the Flu model." (PMID 30510554, 2018). "We next studied the effect of blocking LAG-3 and PD-1 using antagonist mAbs, on viral infection, disease, and anti-viral CD8+ T cell response during the acute phase of HSV-1 infection." (PMID 30619285, 2018). "LAG-3 is a well-described marker of exhausted CD8+ T cells during chronic viral infections, including HIV." (PMID 24743648, 2014). "Taken together, these studies indicate that LAG-3 plays an inhibitory role on immune functions that facilitate persistent viral infections, but allow for the maintenance of self-tolerance." (PMID 25122007, 2014). "However, in chronic inflammatory conditions like cancer or long-term viral infections, there is a notable increase in the expression of LAG-3 on the outer membrane of tumor-infiltrating lymphocytes, including regulatory T cells." (PMID 38390331, 2024).
viral infection (continued). "The up-regulation of LAG-3 during viral infection may generate an incomplete cytotoxic response that impairs viral clearance and immunological memory." (PMID 36680187, 2023). "However, it has also been described that using LAG-3 inhibitors can help overcome immune exhaustion during persistent inflammatory states, such as cancer and viral infections." (PMID 36680187, 2023). "In humans, overexpression of LAG3 is correlated with disease progression in viral infections." (PMID 35400088, 2022). "Finally, LAG-3 and PD-1 are coexpressed in exhausted T cells in viral infection and on TILs, and blockade of both LAG-3 and PD-1 has been demonstrated to have synergistic effects in mouse models." (PMID 28515726, 2017). "However, the expression of TIM-3 and LAG-3 in PAMs of viral infection has scarcely been studied." (PMID 36992486, 2023). "Consistent with chronic viral infection resulting in diminished Th1 differentiation and function, our integrated scRNA-seq analysis demonstrated that the proportions of both Ly6c-hi and Lag3-hi Th1 cells were dramatically reduced during chronic vs acute LCMV infection." (PMID 36255051, 2022). "Notably, Tfh differentiation was also reported to be enhanced by anti-PD-1 and anti-LAG3 treatment during Plasmodium yoelii infection of mice, indicating that this pathway is restricting Tfh differentiation in persistent parasitic, as well as viral infection." (PMID 29951052, 2018). "Collectively, these data indicate that the function of Egr2 and 3 in regulation of clonal expansion differs from their roles in NFAT-mediated anergy and Lag3-Treg cells, demonstrating that distinct mechanisms regulate T cells under homeostatic conditions and during viral infection." (PMID 28487311, 2017). "Positive expression of iRs such as PD1, CTLA-4, TIM3, LAG-3, 2B4, CD160, and BTLA has been directly linked to reduced cytokine production by T cells from cancer patients (including reports from our group) or in the chronic LCMV mouse model of “T cell exhaustion” and other viral infections." (PMID 24391639, 2013). "Contrary to the mass cytometry findings, LAG3 (lymphocyte activating gene) expression was reduced in MIS-C and bacterial infection in comparison with viral infections." (PMID 39300098, 2024). "Several research papers suggest that expression of co-inhibitory molecules such as PDCD1 (PD-1), HAVCR2 (Tim-3), CTLA4, and LAG3 correlates with the activated and more differentiated state of CD8+ T cells in viral infection." (PMID 37409113, 2023). "The coinhibitory molecules TIM3, LAG3 and IDO1 have been poorly examined along porcine viral diseases." (PMID 36713151, 2022). "Having correlated gene-specific viral integration with elevated PD-L1 and PD-L2 expression in HPV-positive HNSC, we next correlated any viral infection with PD-L1, PD-L2, PD-1, CD80, CD86, CTLA-4, Tim-3, LAG3, and 4-1BB expressions." (PMID 30911684, 2019). "We found, after 8 days of viral infection, that in CD169-DTR mice, Tet-GP33+ CD8+ T cells are more highly activated than in WT mice, as determined with granzyme B (GzmB), CD43, PD-1 and Lag3." (PMID 27809306, 2016). "Recent research has focused on the role of specific immune checkpoints, namely TIM-3 T-cell immunoglobulin and mucin-domain containing-3 (TIM-3), lymphocyte activation gene-3 (LAG-3) and programmed cell death protein 1 (PD-1), in modulating immune responses during viral infections." (PMID 38792573, 2024). "Unlike virus-specific T cells, which had sustained expression of inhibitory receptors during chronic viral infection, bacteria-specific Tm cells did not express high levels of inhibitory molecules (PD-1, LAG-3 and TIM-3)." (PMID 38547316, 2024). "We did not observe elevated expression of PD-1, TIM-3 and LAG-3 on OVA-specific T cells at any time-points during chronic virus infection." (PMID 38547316, 2024).
viral infection (continued). "However, an in vivo study evaluated and compared the role of LAG-3 in both chronic and acute viral infections, resulting in a similar intrinsic cellular effect of LAG-3 in both cases, thus supporting the use of LAG-3 blockers to enhance CD8+ T cell responses." (PMID 36680187, 2023). "Future study should be explored how LAG-3 and TIM-3 act to modulate immunity in viral infections." (PMID 36992486, 2023). "Similarly, exhaustion markers Lag3, Tigit, and Ctla4 were uniformly increased in all CD4+ T cell subsets responding to chronic viral infection." (PMID 36255051, 2022). "Of note, the correlation between LAG-3 and PD-1 observed in EBV-associated pediatric cHL, not proved on the non-associated cases, supports the notion of viral infection to promote exhaustion." (PMID 35992809, 2022). "In this study, the upregulated expression of CTLA-4, LAG-3, 2B4, and TIGIT were observed in CD8+ T cells and CD4+ T cells of mice infected with FMDV, which would inhibit T-cell proliferation and promote T-cell apoptosis during virus infections." (PMID 34960627, 2021). "Moreover, LAG-3 pathway also regulates the function and homeostasis of CD8+ T cells during chronic viral infection." (PMID 30619285, 2018). "The overall transcriptional signature we observe is a broad one, with an induction of ISGs (not unexpected in a context of viral infection), but also of cell proliferation, and of heightened effector functions (ENTPD1, LAG3, LRRC32)." (PMID 34433692, 2021). "Furthermore, their CTLs expressed PD-1 and LAG-3, but not CD244 and CD160, at significantly higher levels than those of non-leukemic mice, a phenotype resembling exhaustion during chronic virus infection." (PMID 26658107, 2015).
glioblastoma (35 papers, 2017 to 2026). The most malignant astrocytic tumor (WHO grade IV). "Further research should focus on understanding the role of LAG-3 in the tumour microenvironment and investigating the potential of anti-LAG-3 mAb in glioblastoma." (PMID 38660136, 2024). "LAG-3 expression has been observed in human glioblastoma samples and its inhibition has shown efficacy against glioblastoma in preclinical studies." (PMID 38660136, 2024). "In both glioblastoma multiforme (GBM) and lower-grade glioma (LGG), ALPK1 showed a significant positive association with four immune checkpoints: PD-L1 (CD274), CTLA-4, LAG-3, and PD-1 (PDCD1)." (PMID 39845963, 2024). "Clinical trials have confirmed the safety of combining anti-LAG-3 and anti-PD-1 treatments in glioblastoma." (PMID 38660136, 2024). "LAG-3 expression has been demonstrated in human glioblastoma, and LAG-3 inhibition, or knockout, has been shown to have anti-GBM effects in a murine model." (PMID 36768342, 2023). "TIM-3 was also reported to coexpress with two other checkpoint receptors LAG-3 and PD-1 on severe exhausted tumor-infiltrating lymphocytes of patients with glioblastoma." (PMID 35494006, 2022). "The expression and function of LAG-3 in the TME was investigated in glioblastoma by Harris-Bookman and co-workers, who demonstrated its expression mainly in TIL." (PMID 33920505, 2021). "To date, two clinical trials are ongoing using anti-LAG-3 antibodies as a therapeutic strategy for children affected by glioblastoma." (PMID 33920505, 2021). "Although the expression of CD3, CD8, appear to directly correlate with AGER, the expression of T cell inhibitory genes, such as PD-1 and LAG3 were also higher in RAGE-over-expressing glioblastomas." (PMID 34975408, 2021). "In regard to CNS, anti-LAG3 monoclonal antibodies are being currently investigated in the case of recurrent glioblastoma multiform, being able to cross the blood–brain barrier (Trial ID NCT02658981)." (PMID 32340360, 2020). "They found that when compared to no treatment group mice, the combination therapy significantly affected survival (P ═ 0.03); moreover, there was a clinical trial involving the combination of anti-LAG-3 and anti-PD-1 in the treatment of glioblastoma (NCT02658981)." (PMID 38581716, 2024). "Moreover, they setup an orthotopic preclinical model of glioblastoma and observed that combined therapy using anti-LAG-3 and anti-PD-1 antibodies was more effective in terms of increased overall survival than the single therapy." (PMID 33920505, 2021). "An antibody directed to LAG3 is in clinical trial combined with nivolumab for the treatment of glioblastoma (NCT02658981) while the antagonist LAG-3 mAb (LAG525) is in a phase I/II study as a combination treatment with PD-1 inhibition in solid tumors (NCT02460224)." (PMID 30621125, 2019). "A study conducted in a mouse glioblastoma model proved that LAG-3 inhibition with a blocking antibody is efficacious against glioblastoma and can be used in combination with other immune checkpoint inhibitors toward the complete eradication of model glioblastoma tumors." (PMID 36077354, 2022). "In glioblastoma samples, HVEM expression was shown to coincide with TIM-3, PD-1, PD-L1, CTLA-4, LAG-3, and VISTA." (PMID 40895574, 2025). "We have confirmed co-expression of cystatin F with immune-related markers (CD45, LAG3, TIM3, PD1 and DNAM1) on a protein level in glioblastoma tissue sections." (PMID 41229419, 2025). "In line with our study, intratumoral T cells in glioblastoma were recently found to express multiple immune checkpoints, including PD1, TIM3, LAG3, TIGIT, and CD39, signs of a severe exhaustion signature amidst T cells." (PMID 36497232, 2022). "We found that only a small subset of tissue samples exhibited sparse infiltration by LAG-3+ TILs, and all of them were IDH-wt glioblastoma cases." (PMID 33651248, 2021).
glioblastoma (continued). "It has been proposed that distinct co-inhibitory mechanisms are involved; besides the PD-L1/PD-1 axis, LAG3 and, more recently, TIGIT have been detected in glioblastoma T-cells." (PMID 32899203, 2020). "To date, no other clinical trials investigating LAG-3 blockade therapy in glioblastoma are under investigation." (PMID 39346924, 2024). "In glioblastoma, LAG-3 is expressed along with CD8A, suggesting that LAG-3 targeted therapy in glioblastoma with sufficient CD8+ T cell infiltration may be hopeful." (PMID 37077370, 2023). "Furthermore, glioblastomas upregulate multiple immune checkpoints such as PD-1, TIM-3, LAG-3, and CTLA-4, that facilitate T cell exhaustion." (PMID 34975408, 2021).